CD63 (CD63 molecule)
Diseases named in the same sentence as CD63 in open-access papers (continued):
Sharing a sentence is not in itself a finding about the gene and the disease.
colorectal cancer (14 papers, 2012 to 2025). A primary or metastatic malignant neoplasm that affects the colon or rectum. "Consistently, CD63+-EVs were previously reported to be increased in colorectal cancer patients compared to HCs." (PMID 35350978, 2022). "Such “switch-on” and enhancement fluorescence profiling was shown to distinguish healthy from colorectal cancer patient samples using either CD63 or EpCAM." (PMID 34855021, 2021). "First, we tested the molecular profiling capabilities of the approach using EVs derived from human breast and colorectal cancer cell lines and from plasma of colorectal cancer patients to recognize the tetraspanin protein CD63 and the epithelial cell adhesion molecule (EpCAM)." (PMID 41373484, 2025). "Indeed, it has been reported that the presence of CD63 in vesicles derived from different colorectal cancer cell lines depended on whether the cell growth occurred in a 2D versus 3D culture system." (PMID 32886718, 2020). "The study began by determination of the differences in the abundance of CD63 and HER2 in the EVs prepared from colorectal cancer cells (HT‐29), breast adenocarcinoma cells (SKRB3) and hepatocellular carcinoma cells (HepG2)." (PMID 39221546, 2024). "In the present study, we investigated the tetraspanin family proteins CD63, CD9 and CD81 as useful collection markers of exosomes derived from the three colorectal cancer (CRC) cell lines HCT-15, SW480 and WiDr." (PMID 22895844, 2012).
gastric cancer (14 papers, 2011 to 2024). A primary or metastatic malignant neoplasm involving the stomach. "Positive expression of CD63 was significantly associated with scirrhous gastric cancer, tumor depth, lymph node metastasis, lymphatic infiltration, and tumor size." (PMID 39703839, 2024). "Thus, although increased CD63 expression in gastric cancer cells is suggested as a prognostic factor, it cannot be directly linked to the functions of EVs released by gastric cancer cells." (PMID 33813952, 2021). "Recently, CD63 has been considered as a prognostic marker for patients with gastric cancer and CD63+ Exo might be associated with the interaction between stromal cells and cancer cells." (PMID 31281356, 2019). "Considering these data, CD63-positive exosomes of gastric cancer might also be associated with metastatic niche formation." (PMID 30222750, 2018). "Taken together, these results suggested that decreased levels of CD63 were associated with a high pTNM staging and CD63 may served as a marker for metastatic potential of gastric cancer." (PMID 21521534, 2011). "CD63 positivity in gastric cancer cells or gastric cancer stromal cells is significantly correlated with lymph node metastasis, so it is inferred that CD63-positive exosomes of gastric cancer might also be associated with metastatic niche formation, probably by binding with and inhibiting TIMP1." (PMID 34109113, 2021). "Chen Xiaoming collected 595 cases of gastric cancer patients and analyzed the expression of CD63 in tumor cells and stromal cells using immunohistochemistry." (PMID 39703839, 2024). "Multivariate analysis showed that CD63 expression in cancer cells was a significant independent prognostic factor in patients with gastric cancer." (PMID 30222750, 2018). "Correlation between CD63 expression and clinicopathologic factors in 595 patients with gastric cancer." (PMID 30222750, 2018). "Western blotting revealed that exosomes purified from DSGOST or TJ-38-treated gastric cancer cells were highly positive for the exosome markers, such as CD63." (PMID 29844404, 2018). "Exosomes derived from DSGOST or TJ-38-treated gastric cancer cells were highly positive for the exosomal marker protein CD63 and the upregulation of Slug and Snail was found within these exosomes." (PMID 29844404, 2018). "In this study, we found that CD63 expression in gastric cancer cells was an independent significant prognostic factor." (PMID 30222750, 2018). "The 5-year survival rate of CD63-positive tumor patients was significantly lower than that of CD63-negative tumor patients (p<0.001), suggesting that the expression of CD63 is an important independent factor for the prognosis of gastric cancer patients." (PMID 39703839, 2024). "Chen’s lab found the expression level of CD9 and CD63 was decreased in gastric cancer." (PMID 34222025, 2021). "Because CD63 is a surface marker of exosomes, our data might suggest that exosomes derived from gastric cancer cells play an important role in cancer progression." (PMID 30222750, 2018). "Thus, the object of this study was to clarify the clinical significance of CD63 expression in cancer cells and stromal cells in patients with gastric cancer." (PMID 30222750, 2018). "CD63 expression was an independent prognostic factor in this analysis, and thus might be a prognostic marker for patients with gastric cancer." (PMID 30222750, 2018). "We evaluated the CD63 expressions of cancer cells and stromal cells in 595 gastric cancer tissues." (PMID 30222750, 2018). "Furthermore, the downregulation of CD63 also promotes metastasis and CD63 may serve as a marker for metastatic potential of gastric cancer." (PMID 34222025, 2021). "CD63 might be a prognostic marker for patients with gastric cancer." (PMID 30222750, 2018). "In conclusion, CD63 might be a prognostic marker for patients with gastric cancer." (PMID 30222750, 2018).
gastric cancer (continued). "Here, we focus on the insights into the roles and molecular mechanisms of three tetraspanins involved in gastric cancer cell metastasis, CD9, CD63, and CD82 (also known as KAI1)." (PMID 34222025, 2021). "In summary, the dominant view is that CD9, CD63, CD82 are metastasis suppressors and are negatively correlated with gastric cancer progression and lymph node metastasis." (PMID 34222025, 2021). "Western blotting analysis of CD63 and CD81 of exosomes from EBV-infected gastric cancer cell lines indicated an increase in exosome secretion." (PMID 33198173, 2020). "CD63 and CD81, which are exosome marker proteins, were evaluated in cell lysates and exosome samples from gastric cancer cell lines." (PMID 33198173, 2020). "We found that the gastric cancer cell-derived exosomes (GC-Ex) displayed sphere-like morphology with a diameter ~100 nm and expressed the exosomal markers CD9 and CD63." (PMID 30292233, 2018). "And in the future, we can also establish a gastric cancer cell model overexpressing CD9, CD63 or CD82, by using a plasmid vector." (PMID 21521534, 2011). "The aim of this study was to clarify the clinical significance of TM4SF members CD9, CD63 and CD82 in human gastric carcinoma." (PMID 21521534, 2011). "The reduction of CD9, CD63 and CD82 expression are indicators for the metastatic potential of gastric carcinoma cells." (PMID 21521534, 2011). "The classification of gastric cancers according to CD9, CD63 and CD82 expression might be useful in identifying patients for whom intensive adjuvant therapy is warranted." (PMID 21521534, 2011). "However, the significance of CD63 in patients with gastric cancer has not been fully investigated." (PMID 30222750, 2018).
colon carcinoma (13 papers, 2019 to 2025). "It was found that advanced grades of colon carcinoma correlated with increased immunostaining for Pak1 (a driver of macropinocytosis), CD63 (a MVB/late endosome marker), and V0a3 (a lysosomal V-ATPase marker)." (PMID 37902809, 2023). "Over-expression of human AZIN2 cDNA in T84 colon cancer induced accumulation of CD63-positive exosomes in the culture medium." (PMID 30768610, 2019). "For sEVs recovery experiments, we used the human colon cancer cell line, HT29-CD63-Nluc, which ectopically expresses Nanoluc, a highly sensitive luciferase fused with CD63, as an sEV marker." (PMID 36710884, 2022). "In the current study, the CDEs isolated from human colon cancer cell line SW480 and HCT116 showed a size range of 60–150 nm, typical bilayer-encapsulated vesicles, and expressed the exosomal markers CD81 and CD63." (PMID 31402975, 2019). "However, the role of CD63 in CRC is unclear although, along with α3-Integrin, it showed higher expression in human colon carcinoma cells with spontaneous metastatic ability." (PMID 38391955, 2024).
hepatocellular carcinoma (13 papers, 2014 to 2025). A malignant tumor that arises from hepatocytes. "Huh7.5 hepatoma cells harboring gene knock-outs in CD63 and CD81 were electroporated to express Jc1_R2A, and luciferase activity was measured as a proxy for viral genome replication and spread." (PMID 38357447, 2024). "The two most down-regulated proteins, CD63 and CD81, which is one of the HCV entry receptors, were independently confirmed upon electroporation of Huh7.5 hepatoma cells with a viral genome RNA encoding for a fluorescently labeled NS5A fusion protein (Jc1_NS5A-eGFP)." (PMID 38357447, 2024). "CD63 was present in exosomes derived from hepatoma Huh-7 or Hep3B cells." (PMID 29963269, 2018). "TM4SF5 expression is positively correlated with tumorigenic CD151 expression, but is negatively correlated with tumor-suppressive CD63 expression in mouse fibrotic and human hepatic carcinoma tissues, indicating cooperative roles of the tetraspanins in liver malignancies." (PMID 25033048, 2014). "CD63 is the only known membrane receptor that directly interacts with TIMP1 in numerous malignancies, including hepatocellular carcinoma and other inflammatory diseases." (PMID 35140332, 2022). "In the inflammation category, Lgals1 (Galectin-1), an important immune response modulator and biomarker for hepatocellular carcinoma (HCC) was also markedly increased in SO-HFD but not HFD, as were Abcd2, Cd63, Ly6d and Ubd." (PMID 26200659, 2015).
anaphylaxis (11 papers, 2016 to 2025). An acute hypersensitivity reaction that occurs from exposure to an allergen. "A study of 18 patients with cefazolin perioperative anaphylaxis confirmed by IDT found that BATs using CD63 or CD203c were 38–75% sensitive, respectively." (PMID 39335714, 2024). "Skin tests performed 47 days after anaphylaxis showed a positive result only for butylscopolamine among the exposed agents, which was confirmed by basophil activation tests using CD203c and CD63 as markers." (PMID 32270308, 2020). "This was mirrored by a small but significantly higher percentage of CD63-activated basophils during anaphylaxis compared with that seen in control subjects with venom allergy (median, 3.1%; P = .01) or healthy control subjects (median, 2.4%; P = .001)." (PMID 28342911, 2017). "We observed an increase in the percentage of cells that upregulate CD203c in the patients with anaphylactic shock and in the percentage of cells that upregulate CD63 in patients with anaphylaxis, although these differences were not significant." (PMID 27281069, 2016). "In patients allergic to moxifloxacin with anaphylactic shock, we have observed an increase in the percentage of cells that upregulate CD203c, whereas patients with anaphylaxis preferentially upregulate CD63." (PMID 27281069, 2016). "The study proved correlation between clinical reactions severity and basophils reactivity.L-ASA increases basophil activation to Pru p 3 in patients with FDNIA, as measured by CD63 expression.This finding supports the potential utility of BAT in diagnosing anaphylaxis involving cofactors." (PMID 41226443, 2025). "As CD63 expression of basophils only occurs in anaphylaxis, tolerance of culprit venom in allergic patients could be evaluated using conventional BAT replacing sting challenge." (PMID 36104791, 2022). "Moreover, we compared the expression of activation markers, CD63 and CD203c, in the 2 most frequent clinical entities, anaphylaxis and urticaria, obtained after incubation with their respective culprit FQ." (PMID 27281069, 2016). "However, when the same analysis was done including only positive patients, we observed a higher increase in CD203c in the anaphylactic shock patients compared with CD63, whereas in patients suffering from anaphylaxis, we observed an increase in CD63 cells." (PMID 27281069, 2016). "Therefore, CD63 may be particularly useful in the diagnosis of patients with a history of anaphylaxis, while CD203c may be more relevant for other patient groups." (PMID 41226443, 2025). "In this work, we have analyzed 2 different basophil activation markers, CD63 and CD203c, to diagnose immediate reactions to MOX and CIP in a well-characterized population with a high proportion of severe reactions, including anaphylaxis and anaphylactic shock (70.6% of cases)." (PMID 27281069, 2016).
Stroke (11 papers, 2011 to 2025). Sudden impairment of blood flow to a part of the brain due to occlusion or rupture of an artery to the brain. "Platelet activation markers (CD62P and CD63) were measured by flow cytometry at different time points after stroke and analyzed with clinical outcome." (PMID 21740551, 2011). "The present observations that CD63-labeled exosomes were upregulated after stroke may signal a neuroprotective mechanism." (PMID 38069179, 2023). "In addition, it was also shown that CD62P expression declines during the first weeks after stroke, whereas CD63 expression remains increased for at least 3 months after stroke." (PMID 27036108, 2016). "Interestingly, CD63 expression was shown here to be significantly pronounced and co-localized with angiogenic marker VEGF compared to glial marker GFAP or neurogenic marker MAP2, suggesting that the CD63-labeled extracellular vesicles preferably mediated host angiogenesis after stroke." (PMID 38069179, 2023). "AEVs derived from reactive astrocytes with anti-inflammatory properties possess CD63 and CD9 tetraspanins and miR-146a-5p, which regulate glial scars by suppressing NF-κB and TNF-α, which permit axonal outgrowth, thereby improving stroke recovery." (PMID 37676390, 2024). "Furthermore, the intracerebral administration of AEVs derived from ischemic astrocytes with anti-inflammatory properties, including CD63 and CD9 tetraspanins and miR-146a-5p, induced anti-inflammatory responses in the peri-infarct glial scars and facilitated stroke recovery." (PMID 37676390, 2024). "The CD62P and CD63 expressions on platelets were significantly lower in the patients with pre-existing statin use compared to the patients without pre-existing statin use on Day 1 post-stroke (p < 0.05)." (PMID 21740551, 2011). "In a prospective study of 54 cases of non-CE stroke, those with LVD were found to have significantly higher platelet expression of CD63 during the acute phase, and significantly higher CD62P (P-selectin) expression up to 30 days post event, thus indicating higher levels of platelet activation." (PMID 24988537, 2014).
asthma (10 papers, 2019 to 2025). "Basophils in acute asthma exacerbation are activated as evidenced by their increased expression levels of activation markers such as CD203c and CD63." (PMID 36685514, 2022). "Our pilot study indicates that a CD63-based BAT has potential clinical value for predicting asthma outcome in young children with wheezing episodes." (PMID 33407109, 2021). "Despite the low wheezing frequency in our subjects, the performance of the CD63-based BAT for predicting asthma diagnosis in our study was similar to that of API." (PMID 33407109, 2021). "Our pilot study indicates that CD63-based BAT has potential clinical value for predicting asthma outcome in young children with wheezing episodes." (PMID 33407109, 2021). "Before and after the pollen season, questionnaires were answered for allergic rhino-conjunctivitis, asthma, and medication; serum IgE was measured, and Bet v 1-induced basophil activation was determined by CD63 expression." (PMID 31581605, 2019). "CD63 has been considered to be an activation marker of basophils, and increased CD203c+ basophils were observed in the blood of patients with asthma exacerbation." (PMID 36032674, 2022). "After stimulation with the inhalant mixture, the CD63 expression on basophils and the rate of positive CD63-based BAT results in children diagnosed with asthma were both significantly higher than those in children who were not diagnosed with asthma (p < 0.05 and p < 0.01, respectively)." (PMID 33407109, 2021). "Asthmatics BALF exosomes showed higher levels of tetraspanins CD81 and CD63, of HLA-DR, and CD36, a scavenger receptor with a potential role in asthma exacerbations in response to bacterial infections, compared to healthy controls." (PMID 38957448, 2024). "Saliva EVs from this cohort of children with asthma are 64.95 nm in diameter on average, with a median of 55.09 nm, as reported by TEM, and express mostly CD9 and CD63." (PMID 34368811, 2021). "Upregulation of CD203c proved to be a more consistent activation marker than CD63, and increased expression of CD203c but not CD63 on basophils is accompanied by asthma exacerbation." (PMID 40534099, 2025). "The CD63 expression levels and positive rates of the CD63-based BAT were significantly higher in the children diagnosed with asthma than in those who were not diagnosed with asthma." (PMID 33407109, 2021). "For the prediction of asthma, the positive predictive value and negative predictive value of CD63-based BAT was 71.8 and 69.2%, respectively." (PMID 33407109, 2021). "The level of CD63 expression on basophils after inhalant stimulation was also significantly higher in children diagnosed with asthma (60.0% [34.8–84.2%]) than that in those not diagnosed with asthma (29.2% [11.1–77.4%]) (p < 0.05)." (PMID 33407109, 2021). "The positive rate of CD63+-based BAT was significantly higher for the children diagnosed with asthma (85.2%) compared with that for those not diagnosed with asthma (18.2%) (p < 0.001)." (PMID 33407109, 2021). "Increased expression of CD203c, but not CD63 on basophils, is accompanied by asthma exacerbation." (PMID 36032674, 2022). "We presume that this difference in the results may be due to the difference in the study cohort, as upregulation of CD203c and CD63 in blood basophils was observed in asthma patients with exacerbation, but not in patients having stable phase of allergic asthma." (PMID 36685514, 2022).
osteosarcoma (10 papers, 2009 to 2025). A usually aggressive malignant bone-forming mesenchymal neoplasm, predominantly affecting adolescents and young adults. "As a result, CD63 was ubiquitously expressed among human osteosarcoma cell lines, and CD63 knockdown reactivated Stat3 in AMBN-inducible 143B-Luc cells." (PMID 28054649, 2017). "Interestingly, another study of osteosarcoma also reported that knockdown of CD63 resulted in decreased pY705‐STAT3 expression, which supports our findings in HCC." (PMID 33277798, 2021). "McNamara and colleagues described the distribution and co-localization of CD63 and CD81 in lipid rafts and EVs secreted by U-2 osteosarcoma cells." (PMID 41304773, 2025). "Based on osteosarcoma (OS) cell line, we demonstrated that a combination of CD81 and CD63 antibody on ZNI chip yielded the greatest amount of total EVs, with an extra sensitive limit of detection (LOD) of ~104 particles mL-1." (PMID 34527582, 2021). "Previously, we found that AMBN promoted osteogenic differentiation via the interaction between CD63 and integrin β1, leading to the inactivation of Src; however, how AMBN affects the malignant behavior of osteosarcoma is still unclear." (PMID 28054649, 2017). "CD63 and CD81 were detected in the exosomes produced from osteosarcoma cells by flow cytometry." (PMID 32673448, 2020). "Moreover, we found that cell lines of other tumor histotypes (osteosarcoma and CRC) secreted exosomes expressing variable levels of CD63 and Cav1, in line with the reported cellular expression of Cav1 in these cancers." (PMID 19381331, 2009).